IL4 (interleukin 4)
Diseases named in the same sentence as IL4 in open-access papers (continued):
Sharing a sentence is not in itself a finding about the gene and the disease.
lupus nephritis (14 papers, 2013 to 2026). Glomerulonephritis in the context of systemic lupus erythematosus. "Another study reported that serums IL-18, IL-4 and IL-17 were identified as reliable biomarkers in type-IV lupus nephritis patients." (PMID 31697750, 2019). "Proinflammatory chemokines (MCP-1) and cytokines (IL-6, TNF-α), Th1 cytokines (IL-2, IFN-γ), Th2 cytokines (IL-4, IL-10), and Th17 cytokines (IL-17A) are involved in pathogenesis of lupus nephritis, and are therapeutic targets for lupus nephritis." (PMID 27846813, 2016). "As expected, the serum level of Th1/Th2 cytokines IL-18/IL-4 was significantly higher in LN-IV compared to other groups of lupus nephritis LN-III (p = 0.001), LN-V (p = 0.005), and healthy control (p < 0.0001)." (PMID 27738386, 2016). "Stimulation with CD134-Fc fusion protein further reduced the production of both Th1 and Th2 cytokines including IL-4, IL-10, and IFNγ in patients with lupus nephritis, suggesting the potential role of anti-CD134 in reducing IL-4- and IL-10-mediated renal inflammation." (PMID 24000287, 2013). "IL-4 was elevated in SLE patients with nephritis, correlating with IL-6, IL-10, sCD40L, and IL-8, suggesting B cell involvement in lupus nephritis." (PMID 39379404, 2024). "We found that CKD-506 significantly decreased levels of IFN-γ, IL-1β, IL-4, IL-6, IP-10, MCP-1, and CCL4 in the kidney extracts of mice with lupus nephritis." (PMID 30470828, 2018). "However, the slight increase in GATA3 and IL‐4 in probiotic‐treated groups suggests potential subtle effects on Th2 pathways, which warrant further investigation, particularly in contexts where Th2 responses may play a secondary role, such as in lupus nephritis." (PMID 41334229, 2025). "Reduction of IFNγ levels could improve the outcome of lupus nephritis by inactivating B7/CD28 signalling pathway, which results in a reduction in ANA autoantibodies, IL-4 and IFNγ levels." (PMID 34386197, 2020). "Thus, for the first time, we demonstrated that TGP may be a potent drug to treat lupus nephritis by inducing F4/80+CD11b+CD206+ and F4/80+CD11b+PD-L2+ macrophages through IL-4/STAT6/PD-L2 signaling pathway." (PMID 34290705, 2021). "Thus, the aim of this research is to determine the plasma levels of IL-25 and Th2-associated cytokines (IL-4, IL-5, IL-6, IL-9, IL-10, IL-13) in SLE patients with (SLE-LN) and without lupus nephritis." (PMID 31697750, 2019).
multiple myeloma (14 papers, 2008 to 2026). "Pairwise protein analysis confirmed cosecretion of IL-1β and IL-6 in macrophages stimulated with IL-4/IL-13, which were identified as part of a critical pathway in multiple myeloma before." (PMID 42292686, 2026). "As an example, Semenogelin 1 (SEMG1) expression is positively correlated with the presence of interleukins (IL-4 and IL-6) in multiple myeloma cells." (PMID 37529004, 2022). "At baseline, most Th2 cytokines (i.e., IL-4, IL-5, IL-6, and IL-13) were elevated in the multiple myeloma patients, compared to healthy controls, and most patients had a Th1/Th2 score <1.0, suggesting Th2 dominance." (PMID 34239993, 2021). "Blocking T-cell receptor-MHC-II interaction by anti-MHC-II MoAb (anti-HLADR) completely repressed Th2 cell IL-4 secretion that was promoted by treated-myeloma cells." (PMID 31870332, 2019). "Anti-HLADR IgG2b completely blocked increased of IL-4 secretion by Th2 cells stimulated by treated-myeloma cells, while also blocked enhancing the clonogenicity of treated tumor cells stimulated by MM-Th2 cells." (PMID 31870332, 2019). "We were detected the INF-γ (Th1) and IL-4 (Th2) levels in spleen lymphocytes by ELISA assay in order to further determined cell-mediated immune responses against mice multiple myeloma inoculated NS-1." (PMID 29416605, 2018). "Using GM-CSF/IL-4 bone marrow-derived DCs (BMDCs) for vaccination in combination with pomalidomide and PD-L1 blockade, a significant tumor growth inhibition within a multiple myeloma mouse model could be achieved." (PMID 34054844, 2021). "A recent clinical study has shown that the CD14+ monocytes from multiple myeloma patients could be induced to differentiate into functional DCs by culturing them with the cytokine cocktail consisting of GM-CSF, IL-4, IL-6, TNF-α and IL-1β for use in cancer immunotherapy." (PMID 18533025, 2008). "In serum of 57 patients, we found that IL-4, IL-6, IFN-γ, and TNF-α significantly increased in multiple myeloma compared with healthy control, especially IL-6 and IFN-γ." (PMID 35342422, 2022). "These experiments demonstrated that myeloma cells promote the secretion of IFN-γ, IL-4 and IL-12 by activating Th1, Th2 and CTL cells, respectively." (PMID 31870332, 2019).
sarcopenia (14 papers, 2017 to 2026). Progressive decline in muscle mass due to aging which results in decreased functional capacity of muscles. "Blood was drawn, and inflammatory biomarkers associated with Sarcopenia (IL-2, IL-4, IL-5, IL-6, IL-8, IL-10, TNF, adiponectin, leptin, resistin, BDNF, sTNFr-1 and sTNFr-2) was analysed." (PMID 37365209, 2023). "We also observed enrichment of WIKI-pathway genes in cell cycle, as well as other pathways such as DNA IRdamage and cellular response via ATR, oxidative stress response and IL-4 signaling pathway in the sarcopenia group." (PMID 39026669, 2024). "The results revealed significantly higher expression of genes associated with ERBB, IL-2, IL-4, oxidative stress response and JAK-STAT signaling pathway in the sarcopenia group." (PMID 39026669, 2024). "More specifically, a variety of cytokines, including tumor necrosis factor (TNF)-α, interleukin (IL)-1, IL-2, IL-4, IL-6, IL-8, and IL-10 play a role in the development of sarcopenia." (PMID 36160136, 2022). "The present study investigated the relationship between the plasma pro-inflammatory factors TNF-α and IL-6 and the anti-inflammatory factors IL-4 and IL-10 in the elderly population and sarcopenia." (PMID 36160136, 2022). "In this context, it is reasonable to suggest that IL-4 has potential to be an adjuvant therapeutic target for sarcopenia owing to its multiple activities." (PMID 31814802, 2019). "Regarding the inflammatory markers, we observed that patients with sarcopenia showed a trend of higher levels of hsCRP and lower levels of the anti-inflammatory cytokine IL4." (PMID 28448584, 2017). "Indeed, previous studies reported increased levels of IL-6 and TNF, but also higher IL-4 and IL-10, in patients with sarcopenia with respect to healthy individuals." (PMID 38001845, 2023). "After further correction of plasma IL-10 and IL-4 levels, increased plasma TNF-α level remains associated with sarcopenia, suggesting that immune aging may be involved in the pathogenesis of sarcopenia." (PMID 36160136, 2022). "IL-4 has dual potential to act as an adjuvant therapeutic target for sarcopenia to preserve muscle mass and insulin resistance to improve insulin sensitivity, which implicates the regulation of immune system to the muscle differentiation and exercise performance." (PMID 31814802, 2019). "Therefore, the present study explores the relationship between sarcopenia and IL-4, IL-6, IL-10, and TNF-α in the elderly population of agricultural and pastoral areas of Xinjiang, China, and is expected to lay a preliminary foundation for understanding its underlying mechanism." (PMID 36160136, 2022). "Therefore, it would be intriguing to characterize the IL-4 genotypes in subjects with sarcopenia." (PMID 31814802, 2019). "Two inflammatory cytokines, including TNF-α and IL-4, were selected by PLS-DA to construct a model, which had an overall AUROC of 0.896 (95%CI 0.816–0.954) for sarcopenia." (PMID 36160136, 2022). "Various cytokines involved in the pathogenesis of sarcopenia have been identified in foreign studies and include TNF-α, IL-1, IL-2, IL-4, IL-6, IL-8, and IL-10." (PMID 36160136, 2022). "The present study showed that, even if not significantly, the SO group had higher values of IL-4, more investigation is needed to better comprehend this marker’s role in sarcopenia." (PMID 40100802, 2025). "In the Copenhagen sarcopenia study, elderly women also had significantly higher levels of CRP, TNF-α, and IL-6, compared with middle-aged women and significantly higher levels of CRP, TNF-α, IL-1β, and IL-4 compared with young girls." (PMID 36291982, 2022). "The average levels of the four proinflammatory cytokines, including IL-1β, IL-6, IL-15, and TNF-α, were significantly increased in sarcopenia patients compared to those in young/healthy volunteers, while the concentrations of two other cytokines, IL-4 and IL-13, were not changed." (PMID 32226296, 2020).
sarcopenia (continued). "Of note, serum IL-4 levels were reduced, while IL-6, TNF, VEGF, and MCP-1 concentrations were increased, in patients with sarcopenia compared to those with no sarcopenia." (PMID 38001845, 2023). "Comparisons of living habits, disease status, biochemical indexes, and levels of interleukin (IL)-4, IL-6, IL-8, IL-10, and tumor necrosis factor (TNF)-α in sarcopenia and non-sarcopenia participants were made in this study." (PMID 36160136, 2022).
Airway obstruction (13 papers, 2014 to 2024). Obstruction of conducting airways of the lung. "Th2 cells generate the proinflammatory cytokines IL-4, IL-5, and IL-13, which trigger mast cell and basophil activation, leading to inflammation and airway obstruction." (PMID 39421735, 2024). "When combined with IL-13, IL-4 can promote goblet cell hyperplasia of the airway, and those goblet cells secrete excessive mucus leading to airway obstruction, breathing difficulties, and even death in asthmatic patients." (PMID 33343229, 2020). "Licochalcone A had the ability to reduce goblet cell hyperplasia, reducing excessive secretion of mucus and preventing airway obstruction and asphyxia by blocking expression of IL-4 and IL-13 in BALF and lung tissue." (PMID 31226782, 2019). "Moreover, we found that IL-4 level in bronchial epithelial cells wound closure assay decreased with the severity of airway obstruction, suggesting that IL-4 could be involved in abnormal bronchial epithelial repair in COPD." (PMID 25427655, 2014). "Central to the generation of airway obstruction in the context of allergic inflammation are T cells, especially T helper type 2 (TH2) cells that secrete interleukin 4 (IL-4), IL-5 and IL-13 and Th17 cells that produce the cytokines IL-17A and IL-17F." (PMID 26605551, 2015).
B cell lymphoma (13 papers, 2011 to 2025). "To do so, we used CH12 cells, a murine B cell lymphoma that undergoes efficient CSR from IgM to IgA in response to interleukin 4 (IL4)." (PMID 39341827, 2024). "Apart from helper T cells, various cell types of the B cell lymphoma microenvironment are capable of producing the cytokines IL-4, IL-6, IL-10 and TNFα." (PMID 32899476, 2020). "The function of IL4/IL4R may be to accelerate AITL progression and trigger the transition from AITL to B cell lymphoma, indicating that IL4/IL4R is a potential pharmacological target." (PMID 38145335, 2024). "However, a study conducted on B cell NHL suggests that high expression of IL4, which is secreted by Th2 cells, is strongly correlated with reduced cancer proliferation and increased survival." (PMID 34391381, 2021). "NKG2A blockade potentiated NK cell-mediated ADCC against malignant B cells treated with CD40L and IL-4 and improved anti-CD20 antibody therapy in a murine model of B cell lymphoma." (PMID 40977848, 2025). "Extensive analysis of the transcriptional regulation of AICDA in a murine mature B-cell lymphoma cell line had revealed that CD40L, IL-4, and TGFβ induce AICDA expression via NF-κB, Stat6 and Smad3/4 signaling, respectively." (PMID 33507341, 2021). "The increased levels of TNF-α, IL-12 and IFN-γ and undetectable levels of IL-4 and IL-10 suggest that TME in lacrimal gland B-cell lymphoma was polarized toward Th1 pattern, which is similar to what were previously observed with an intraocular B-lymphoma." (PMID 29029511, 2017). "Interestingly, an alternative mechanism of constitutive IL-4 signaling and STAT6 activation independent of external IL-4 stimulation has been reported for another B cell lymphoma subtype, primary mediastinal B cell lymphoma (PMBL)." (PMID 35851155, 2022).
bladder cancer (13 papers, 2012 to 2025). "High urinary concentrations of IL4 were recently associated with poor recurrence-free survival in patients with bladder cancer, but the exact role of IL4 in bladder regeneration and bladder tumorigenesis still remains elusive." (PMID 31779626, 2019). "Moreover, the CCR2 -V64I polymorphism is potentially associated with the incidence of cancers including oral, cervical, and bladder cancers, while IL4 rs2243250 and rs79071878 have been linked to oncogenesis in certain cancers and ethnic groups." (PMID 38807156, 2024). "This immune suppression allows bladder cancer to recruit Th2 cells and TAMs, increasing IL-4 secretion and further suppressing cytotoxic T cell production, promoting metastasis, immune evasion, and tumor growth." (PMID 40699676, 2025). "IL-4 modestly inhibited the cell proliferation, but enhanced cell invasion of bladder cancer cell lines in a concentration-dependent manner." (PMID 25208941, 2014). "Our observation in this experiment is consistent with a recent report showing that the circulatory levels of IL-4, IL-5, and IL-10 were significantly higher in bladder cancer patient serum than in normal samples." (PMID 22962576, 2012). "Thus, LINC00702-activated DUSP1 suppresses bladder cancer cell proliferation and inhibits the secretion of inflammatory cytokines IL-4, IL-10, and TNF-α M2-OAM in bladder cancer." (PMID 38139370, 2023). "Basophils may have a role in BCG-treated bladder cancer patients because of their ability to facilitate Th2 polarization by secreting proinflammatory interleukins (IL-4 or IL-13) and skewing antigen-presenting cells towards a type 2 response." (PMID 33343662, 2020). "We observed that exogenous IL-4 could only modestly inhibit the growth of bladder cancer cell lines in vitro." (PMID 25208941, 2014). "We also examined the effect of IL-4 on proliferation and invasion of bladder carcinoma cell lines." (PMID 25208941, 2014). "Concurrently, SKA3 expression was positively correlated with the expression level of Th2 cell markers (IL-4 and CCR3) in bladder cancer." (PMID 35546682, 2022). "The impact of Dupilumab on cancer inhibition has not been established due to its recent development, but the IL-4 blockade mechanism shows promise for future immunotherapy in bladder cancer." (PMID 40699676, 2025). "In addition, SKA3 expression in bladder cancer was significantly correlated with M2 macrophage markers, including MRC1 and CD163, and Th2 cell markers, including CCR3 and IL-4." (PMID 35546682, 2022).
childhood asthma (13 papers, 2012 to 2025). "In the case of the rs2243250 polymorphism of the IL-4 gene, individuals with the T allele had 1.17 times higher odds of childhood asthma than those with the C allele." (PMID 38699097, 2024). "The present study aims to investigate the genetic aberrations, specifically single nucleotide polymorphisms (SNPs) of IL-4 and IL-13, and their association with childhood asthma and its severity." (PMID 38699097, 2024). "During pregnancy, the maternal ratios of IFN-γ/IL-13 and IFN-γ/IL-4 are associated with a lower prevalence of childhood asthma." (PMID 34409053, 2021). "Additionally, in Xinjiang Uygur, several studies have found that IL-4 and IL-13 gene polymorphisms are associated with childhood asthma." (PMID 36313877, 2022). "In the ADEM study, the minor alleles of ADAM33 rs511898 and rs528557 and the ORMDL3/GSDMB rs7216389 polymorphisms were negatively associated, whereas the minor alleles of IL4 rs2243250 and rs2070874 polymorphisms were positively associated with childhood asthma." (PMID 25768087, 2015). "Another multicentre prospective study reported that higher nasopharyngeal airway type 2 cytokine (IL-4, IL-5, IL-13, and TSLP) levels in infants with HRV infection alone were associated with a greater risk of developing childhood asthma." (PMID 40852413, 2025). "Larger studies are warranted to investigate the combined effects of the SNPs in the IL-4/IL-13 signaling pathway and the interaction with mold exposure on childhood asthma." (PMID 33810791, 2021). "The rationale is that early intervention, particularly with therapies blocking IL-4 and IL-13, might be attractive in childhood asthma, which is often driven by allergen sensitization, eosinophilia, and T2 immunity." (PMID 40486460, 2025). "IL-4 and IL-13 are the critical cytokines that regulate the switching from Immunoglobulin M (IgM) to IgE in activated B lymphocytes and the differentiation of Th2 cells, which is the pathogenesis of allergic inflammation or childhood asthma." (PMID 33810791, 2021). "Therefore, the regulating effect on IgA, IgE, IgG, IL-4, and IFN-γ may be the basic mechanism of acupoint application for childhood asthma." (PMID 26000027, 2015).
chronic kidney disease (13 papers, 2012 to 2026). Impairment of the renal function secondary to chronic kidney damage persisting for three or more months. "Effects of Shenkang injection (SKI) on the levels of CRP, IL-1β, IL-6, TNF-α, IL-4,and IL-10 in serum of chronic renal failure rats*." (PMID 35674582, 2022). "Previous investigations demonstrated the effect of IL-6, IL-4, and ICAM polymorphisms in end-stage renal disease patients." (PMID 31924810, 2020). "Recent studies have shown that curcumin can alleviate inflammation in chronic kidney disease (CKD) by reducing chemokine 2 (CCL-2), interferon-γ (IFN-γ), and interleukin-4 (IL-4) and regulating lipid peroxidation." (PMID 41170356, 2025). "Similar observations have been previously reported for VD on oxidative stress markers and the expression of IL-10, IL-4 and TNF-α in chronic renal diseases and testicular dysfunction." (PMID 29556070, 2018).
migraine (13 papers, 2017 to 2025). "Li Jinhong found that the levels of serum INF-α, IL-2, IL-17, IL-12P70, TNF-α, IL-5, IL-1β, and IL-4 were higher in adult migraine patients than in normal control group, which changed with different stages of the disease." (PMID 38356891, 2024). "The most relevant cytokines related to migraines include IL-1, IL-2, IL-4, IL-6, IL-10, TNF-α, and TGF-β." (PMID 35896985, 2022). "Migraine patients had elevated levels of interleukin-4 (IL4), TGF-β, TNF-α and interferon gamma." (PMID 35432179, 2022). "Remarkably, our results for the first time provided evidence that enhance our understanding of how migraine may relate to, an anti-inflammatory cytokine, IL-4 gene variation." (PMID 29179499, 2017). "In conclusion, serum levels of IL-4, TNF-α, IL-17A, and IL-12p70 are increased in children with migraine." (PMID 38356891, 2024). "Omega-3 fatty acid supplementation increased anti-inflammatory cytokine IL-4 and decreased pro-inflammatory cytokine IFN-γ levels in patients with migraines, suggesting a potential beneficial effect on the inflammatory immune response." (PMID 38770523, 2024). "The levels of folic acid, homocysteine (Hcy), vitamin B12, interleukin-2 (IL-2), IL-4, and ferritin, and changes of NRS were compared between folic acid and conventional treatment groups stratified by different genotypes of MTHFR in migraine patients." (PMID 36619923, 2022). "In studies of non-inflammatory cytokines in patients with migraines, some reports indicated lower or unchanged IL-4 levels compared with during attacks." (PMID 37176049, 2023). "While IL-4 itself is not typically measured in migraine natural history studies, a higher IL-4/TNF ratio, for instance, could hypothetically indicate a less inflammatory milieu and potentially less risk of chronification." (PMID 41377228, 2025). "Interictal studies on IL-4 levels in migraine have yielded few reports with no certainty." (PMID 37176049, 2023).